TNF (tumor necrosis factor)
Diseases named in the same sentence as TNF in open-access papers (continued):
Sharing a sentence is not in itself a finding about the gene and the disease.
Hyperglycemia (continued). "The increased production of TNF was prevented by the addition of the GLUT1 inhibitor Bay-87625, suggesting that the observed effects were due to enhanced glucose internalization upon hyperglycemia." (PMID 41244562, 2025). "Furthermore, hyperglycemia triggers the activation of inflammatory pathways, including the release of cytokines such as vascular endothelial growth factor (VEGF) and tumor necrosis factor-alpha (TNF-α)." (PMID 41153644, 2025). "Chronic hyperglycemia rather than acute hyperglycemia is important in inducing inflammation in the lungs through cytokines such as IL-2, IL-17, and TNF-α (Ngo, Bartlett and Ronacher, 2021)." (PMID 39981106, 2024). "Besides this, hyperglycemia, via NADPH oxidase and due to the stimulative effect on TNF-α realized from monocytes, can contribute to ROS generation." (PMID 39336541, 2024). "Hyperglycemia can contribute to tumor-related inflammation by triggering the release of pro-inflammatory cytokines such as interleukin-6 (IL-6), interferon γ (IFN-γ), tumor necrosis factor-alpha (TNF-α), and resistin." (PMID 39064000, 2024). "In this animal model, when TNF-α-mediated signaling (which was increased in the serum and bladder) was inhibited, overactive bladder was reversed without affecting hyperglycemia." (PMID 39292699, 2024). "Consistent with our in vitro model of hyperglycemia, CD34+ cells from CAD-T2DM patients displayed, a significant upregulation of CDKi p21 and p27 genes as well as upregulation of proinflammatory genes (IL6 and TNFα), and their transcription factor NFkB-p65." (PMID 38553774, 2024). "In this study, we found that type 2 diabetic patients had significantly higher FPG and HbA1c levels, indicating hyperglycemia, and serum TNF-α, an inflammatory marker, than non-diabetic participants." (PMID 36759556, 2023). "Several studies have found that LPS or other factors, such as polymeric immunoglobulin A1 (pIgA1) and hyperglycemia, can activate mesangial cells to produce pro-inflammatory cytokines, including IL-6, transforming growth factor-beta 1 (TGF-beta 1), TNF-α and NO." (PMID 37488573, 2023). "In addition, morphological signs of microglial response to hyperglycemia, as well as increased pro-inflammatory mediators, such as IL-1β, CCL2 and TNF-α, were described." (PMID 36869375, 2023). "TNF-α was higher in patients with hypertension (p=0.002) and hyperglycemia (p=0.017) compared to those without." (PMID 37529617, 2023). "AGEs, which are upregulated by hyperglycemia, bind to RAGE to increase TNF-α secretion." (PMID 37511915, 2023). "Interestingly, hyperglycemia has been reported to activate NLRP3 inflammasomes and downstream effector inflammatory cytokines, including TNF-α and IL-1β, which are believed to induce programmed proinflammatory cell death (pyroptosis)." (PMID 35453376, 2022). "Hyperglycaemia has been shown to increase MyD88 independent and dependent signalling along with pro-inflammatory/angiogenic mediators downstream to MyD88 such as NFκB, VEGF, TNF-α and IL-1β." (PMID 38983565, 2022). "In the absence of hyperglycemia, however, extract of ginger has been demonstrated to considerably lower the manufacturing of excess NF-κB and TNF-α." (PMID 36557312, 2022). "Log IL-10, IL-10/TNF-α ratio, and log CXCL10, but not log IFN-γ were independently associated with stress hyperglycemia." (PMID 36059840, 2022). "Pio also has broad anti-inflammatory activity, exemplified by its ability to significantly reduce interleukin-6 (IL-6) and tumor necrosis factor α (TNFα) in insulin resistant individuals without manifest hyperglycemia matched for age, gender, and adiposity." (PMID 35743273, 2022). "An insulin-resistant metabolism is hallmarked by hyperglycemia, elevated free fatty acids (FFA), and a chronic state of inflammation mediated through cytokines such as interleukin-1β (IL-1β), interferon-γ (IFN-γ), and tumor necrosis factor-α (TNF-α)." (PMID 35453472, 2022).
Hyperglycemia (continued). "Regardless of the postulated mechanisms, the results of our study demonstrated that exposure to TNFα and hyperglycemia did not impact any of these mechanisms in HUVECs." (PMID 34045516, 2021). "Overall, the levels of the KRIS proteins were not altered in intracellular or extracellular fractions of TNFα and hyperglycemia stimulated HUVECs." (PMID 34045516, 2021). "Previous studies have demonstrated that hyperglycemia activates the innate immune response mediated by TLR2, TLR4, and the NLRP3 inflammasome, inducing the production of various proinflammatory cytokines, including IL-1β, IL18, IL-6, and TNFα." (PMID 34356130, 2021). "Hyperglycemia-induced polymorphonuclear (PMN) dysfunction has been related (in patients with and without DM) to a significantly reduced chemotaxis and with increased complications in these patients due to increased secretion of IL-1, IL-6 and TNF-α." (PMID 35096863, 2021). "Our findings indicated that TNF-α likely contributes to hyperglycemia predominately via mitochondrial dysfunction rather than other pathways, but this remains to be confirmed." (PMID 32215181, 2020). "Activation of β-ARs reduced levels of iNOS and other inflammatory molecules, such as interleukin (IL)-1β, tumor necrosis factor-α (TNF-α), and prostaglandin E2 (PGE2) in human retinal endothelial cells and rat Müller cells in an in vitro model of hyperglycemia." (PMID 33287335, 2020). "Through this study, a conclusion could be made that WEM mitigates hyperglycemia, IR, and inflammation through the interactions among TLR2 signalling pathway, insulin signalling pathway and TNF-α." (PMID 31752797, 2019). "Our results indicate that efferent vagal stimulation attenuates hyperglycemia in endotoxemia by inducing insulin and regardless of TNF regulation." (PMID 30700738, 2019). "Angiogenic responses of endothelial cells is induced directly by inflammatory cytokines such as IL-1β, IFN-γ, and TNF-α and indirectly by inducing endothelial cells to produce growth factors rather than a direct effect of hyperglycemia on endothelial cells." (PMID 31337130, 2019). "Indeed, PKC-ζ phosphorylates endothelial p47phox in the presence of tumor necrosis factor-α (TNF-α) and the PKC-β1 isoform promotes hyperglycemia-induced apoptosis of endothelial cells." (PMID 31382355, 2019). "The effect of arterial stiffness on endothelial ROS production in response to an external stimulus such as hyperglycemia or TNF-α has not yet been investigated." (PMID 31110559, 2019). "A significant upregulation in IL-1β (p ≤ 0.01) expression was identified with high hyperglycemia (45 mM) independent of a change in TNF-α expression." (PMID 30470798, 2018). "Inflammatory cytokines, such as tumor necrosis factor-alpha (TNF-alpha) and matrix metalloproteinase-9 (MMP-9) have been demonstrated to be involved in the pathogenesis of DED.Thirdly, hyperglycemia has also been confirmed to lead to histological alterations in the lacrimal gland." (PMID 29747621, 2018). "The increased tumor necrosis factor-alpha (TNF-α) production by mononuclear cells, in response to hyperglycemia, may further intensify metabolic and hormonal abnormalities in PCOS." (PMID 29387832, 2017). "In the present study, we tested the hypothesis that overexpression of miR-146a protects REC from hyperglycemia-induced proinflammatory responses through downregulation of TLR4, NF-κB, and TNFα." (PMID 26997759, 2016). "In our study, an acute increase in PG could increase the plasma levels of IL-6, TNF-α and ICAM-1 and their expression by vascular endothelial cells, and greater inductions were observed following exposure to fluctuant hyperglycemia." (PMID 27496150, 2016). "The aim of our study was to evaluate the effect of low-power laser irradiation at two wavelengths (635 and 830 nm) on the secretion of inflammatory factors (TNF-α and IL-6) by the endothelial cell culture—HUVEC line (human umbilical vein endothelial cell)—under conditions of hyperglycemia." (PMID 26861982, 2016).
Hyperglycemia (continued). "The aim of our study was to evaluate the effect of low-power laser irradiation at two wavelengths (635 and 830 nm) on the secretion of inflammatory factors (TNF-α and IL-6) by the endothelial cell culture—HUVEC line (human umbilical vein endothelial cells)—under conditions of hyperglycemia." (PMID 26861982, 2016). "The hypothesis of this study was that miR-146a plays a key role in attenuating hyperglycemia-induced inflammatory pathways through reduced TLR4/NF-κB and TNFα signaling in primary human retinal microvascular endothelial cells (REC)." (PMID 26997759, 2016). "For instance, hyperglycemia per se, regardless of the presence/absence of concurrent endotoxemic insult, depressed the expression of TNF-α mRNA, but augmented the IL-1β and IL-6 mRNA expression in MLNs." (PMID 26207186, 2015). "Hyperglycaemia did not modify ND-EC function, but TNF-α and palmitate significantly reduced angiogenic capacity (by 27% and 43%, resp)." (PMID 25950006, 2015). "Overexpression of miR-15b and/or miR-16 reduced TNFα and SOCS3 levels, while increasing insulin-like growth factor binding protein-3 (IGFBP-3) levels and the phosphorylation of insulin receptor (IR)Tyr1150/1151 in REC cultured in hyperglycemia." (PMID 25888955, 2015). "We suggest that while IR in critically ill patients is a consequence of systemic inflammation mediated by TNF-α per se, the impaired incretin effect is not directly related to inflammation; it more likely occurs secondary to the development of hyperglycaemia." (PMID 26567860, 2015). "A variety of PSC activating factors (e.g.: EtOH, TGF-β1, PDGF, TNFα, interleukines [IL-1,-6,-13], ROS) were previously identified, but the role of chronic (i.e.>14 days) hyperglycemia in PSC activation has not been investigated to date." (PMID 26010611, 2015). "That suggests that miR-15b may directly or indirectly target IGFBP-3, which contributed to the reduced signaling of TNFα and SOCS3, as well as increased IRTyr1150/1151 phosphorylation to protect REC in hyperglycemia." (PMID 25888955, 2015). "The authors observed a hyperglycemia-induced increase in reactive oxygen species (ROS) and activated NF-κB in patients with PCOS, thus leading to transcription of tumor necrosis factor α (TNFα), most pronounced in obese patients with PCOS." (PMID 24928911, 2014). "Meanwhile, the changes of TNF-α might be better and earlier than those of IL-6 in predicating CAD during postchallenge hyperglycemia in patient with AbnGT." (PMID 22397368, 2012). "It triggers systemic changes like hyperglycemia and hyperinsulinemia and increases levels of adipose tissue-derived estrogens, adipokines, and inflammatory mediators (e.g., prostaglandin E2 [PGE2], tumor necrosis factor [TNF], and IL-6), stimulating cancer growth." (PMID 40040878, 2025). "First, hyperglycemia activates microglial cells via the AGE-RAGE axis, leading to an increase in blood–brain barrier (BBB) permeability, which subsequently promotes the infiltration of pro-inflammatory cytokines such as IL-6 and TNF-α into the brain parenchyma." (PMID 40242624, 2025). "Besides, Hyperglycemia promotes the secretion of pro-inflammatory cytokines including C-reactive protein (CRP), interleukin-6 (IL-6), and tumor necrosis factor-alpha (TNF-α), all of which have been shown to contribute to DKD progression and cardiovascular disease development." (PMID 40747306, 2025). "Luteolin ameliorated hyperglycemia and improved hypoinsulinemia, β-cell dysfunction, and renal impairment in HFD-STZ-induced diabetic rats by attenuating inflammation and dysregulated cytokine secretion through modulation of PPAR-γ, TNF-α, IL-6, and NF-kB expression and down-regulation of SREBP-1c." (PMID 40076380, 2025). "Similarly, in our model, the dual challenge of hyperglycemia and GBS may trigger a tolerization-like response, selectively downregulating TNF-α, MCP-1, and MIP-1β to avoid fetal harm, yet at the cost of impaired immune defense." (PMID 40746553, 2025).
Hyperglycemia (continued). "In line with our in vitro model of hyperglycemia, at the end of differentiation, CAD-T2DM-derived monocytes still showed, as their precursors, high expression levels of CDKi p21 and p27 genes, and release, after LPS stimulation, of proinflammatory IL6 and TNFα cytokines." (PMID 38553774, 2024). "Granular UEA I staining was also observed with IL-6 treatment, which might indicate that IL-6 is the causative factor for glycocalyx damage in the diabetic cocktail, since hyperglycemia or TNF-α treatments alone did not alter UEA I." (PMID 38355716, 2024). "miR-15b and miR-16 can increase the IGFBP-3 levels by reducing the tumor necrosis factor-α (TNF-α) and suppressor of cytokine signaling 3 signaling pathways, which increase RCVEC apoptosis by modulating IRS-1 and protect against apoptosis induced by hyperglycemia in retinal ECs." (PMID 37978169, 2023). "Notably, pretreatment with insulin or metformin did not modify the decreased secretion of TNF-α and IL-6 observed under hyperglycemia." (PMID 36982317, 2023). "Moreover, our results indicated that GQL in T2DM treatment may affect the TNF/NF-κB and PI3K/AKT/MTOR pathways to reduce inflammation and improve hyperglycemia." (PMID 34381354, 2021). "In retinal Müller cells, hyperglycemia- and hypoxia-induced ER stress promotes activation of ATF4, which upregulates inflammatory genes by activation of hypoxia-inducible factor (HIF) and JNK, resulting in the retinal expression of inflammatory cytokine tumor necrosis factor (TNF-α) and VEGF." (PMID 35082783, 2021). "Among the biological factors are hyperglycemia, hyperinsulinemia, overproduction of insulin-like growth factor-1 (IGF-1), increased expression of the IGF-1 receptor, and increased secretion of inflammatory cytokines, such as interleukin 6 (IL-6) and tumor necrosis factor alpha (TNF-α)." (PMID 32473631, 2020). "Ligature was able to induce increased levels of TNF-α and IL-17 in both NH and H. This study revealed the negative impact of hyperglycemia and/or treatment with metformin in the bone repair via inhibition of transcription factors associated with osteoblastic differentiation." (PMID 32841254, 2020). "Therefore, hyperglycemia and hypoxia have a negative effect on inflammation as they upregulate the gene expression of the inflammatory cytokines TNF-α, IL-6 and IL-1 in activated macrophages." (PMID 31415598, 2019). "In this study, it demonstrated that PF could alleviate vascular injuries induced by hyperglycemia fluctuations in terms of the release of TNF-α, PECAM-1, oxidative stress, and the expression of PKCβ1 in HUVECs subjected to intermittent glucose levels and in DM rats with fluctuating hyperglycemia." (PMID 31093316, 2019). "Furthermore, stimulation with both rIL-17 and high glucose was more effective in increasing the expression of inflammatory cytokines IL-6 and TNFα and the chemokine CCL2 than either condition alone, suggesting IL-17 and hyperglycaemia synergistically promote diabetic podocyte injury." (PMID 30783187, 2019). "Indeed, in recent years, the impact of DNA methylation has been documented in DR, where previous reports suggest that hyperglycemia can evoke distinct methylation patterns in the promoters of miRNAs and several DR-related genes (i.e., MMP-9 and TNF), furthering the progression of DR." (PMID 31337130, 2019). "In the present study, we tested the hypothesis that miR-15b and miR-16 levels are altered by exposure to hyperglycemia in REC, and that miR-15b/16 play key roles in regulating insulin signaling through a reduction in TNFα- and SOCS3-mediated insulin resistance pathways." (PMID 25888955, 2015). "Reduced H3K9 methylation was also observed at the IL-1β and TNF-α promoters in LPS-treated THP-1 cells, at the MMP-9 promoter in phorbol 12-myristate 13-acetate–treated HeLa cells and at the NF-κB-p65 promoter in a model of transient hyperglycemia in bovine aortic endothelial cells." (PMID 24886859, 2014).
Hyperglycemia (continued). "In this regard, TNF-α has been hypothesized to exert an inhibitory effect on insulin secretion and insulin-regulated glucose uptake in GDM, thus contributing to the sustained hyperglycemia." (PMID 23691290, 2013). "Chronic hyperglycemia modulates immune responses and triggers inflammation through the activation of Toll-like receptors (TLRs), leading to an increase in the proinflammatory cytokines, IL1, IL6, TNFα and interferon γ(IFNγ), and a decrease in the levels of interleukin 10 (IL10)." (PMID 24260283, 2013). "Hence, diabetic ApoE−/− and ApoE−/−/TNFα−/− mice had both hyperglycemia and hyperlipidemia, whereas wt and TNFα−/− mice exhibited hyperglycemia but no significant changes in plasma lipids." (PMID 20856927, 2010). "However, in fact, hyperglycemia in the blood and significant TNF-α production in the brain were observed in the MD group, whereas blood glucose levels decreased and TNF-α levels in the brain were significantly reduced in the RS-administered group, which may be due to the suppression of pancreatitis." (PMID 40559659, 2025). "This study showed that blood glucose, insulin, HOMA-IR, TG, LDL-C, TCHO, IL-1β, TNF- α showed marked elevation in T2D mice, suggesting that there is hyperinsulinemia and IR in T2D, the body is in an inflammatory state, insulin can not be used normally, which is manifested as hyperglycemia." (PMID 41098781, 2025). "To test this hypothesis, we quantified the gene expression of macrophage-secreted cytokines (IL-1β, IL-6, TNF-α, IL-10) and chemokines (CCL2) in the lacrimal gland, conjunctiva and cornea of non-diabetic normoglycemic mice and diabetic mice with 7, 14, and 28 days of hyperglycemia." (PMID 39749321, 2024). "The possible explanation might be persistent hyperglycemia has a direct relationship with the non-enzymatic glycation of various proteins and the increased expression of pro-inflammatory cytokines such as IL-6, and TNF- α in blood circulation." (PMID 35895700, 2022). "Altogether, these data indicate that the interplay of PDEC with macrophages and hyperglycemia impacts mRNA levels of inflammatory EMT and CSC inducers in both PDEC populations; however, superior effects of concomitant exposure to both factors could only be observed for TNF-α." (PMID 34064969, 2021). "Moreover, hyperglycemia can induce the expression of several proinflammatory cytokines, such as interferon gamma (INF-γ), interleukin-6 (IL-6), and tumor necrosis factor-alpha (TNF-α), leading to the development of a chronic subclinical inflammatory status in DM." (PMID 26770985, 2016). "Specifically, hyperglycemia may facilitate the synthesis of advanced glycation end products (AGEs) that induce oxidative stress via RAGE, activating NF-κB that initiates and regulates inflammation by synthesizing proinflammatory cytokines, including TNF-α, IL-1β, and IL-6." (PMID 26074994, 2015). "Systemically, the intervention effectively alleviated hyperglycemia, HOMA-IR, hyperlipidemia, and serum MDA levels, reduced NAS and liver TNF-α levels, while having no appreciable effect on adiposity, serum insulin levels, or liver IL-6, TG, and TC levels." (PMID 40427484, 2025). "Patients with stress hyperglycemia had significantly higher levels of IL-10, IL-10/TNF-α ratio, CXCL10, and CRP than patients without stress hyperglycemia." (PMID 36059840, 2022). "miR-146a Over-expression decreased TNF-α and TLR4/NF-κB expression levels and abolished MyD88-dependent and non-dependent pathways in the ocular ECs in hyperglycemia condition." (PMID 33995938, 2021). "Therefore, it is possible to suggest that hyperglycemia promotes the development of a chronic low grade inflammation in renal parenchyma, characterized by increased levels of proinflammatory cytokines INF-γ, TNF-α, and IL-6 levels, which may be involved in the pathogenesis of diabetic nephropathy." (PMID 26770985, 2016).